FOXM1 (forkhead box M1)
Diseases named in the same sentence as FOXM1 in open-access papers (continued):
Sharing a sentence is not in itself a finding about the gene and the disease.
breast cancer (continued). "Especially, CDCA5 promoted proliferation, migration and inhibited apoptosis of breast cancer cells, which was alleviated by silencing FOXM1." (PMID 38978058, 2024). "Growth suppression of breast cancer cells by FOXM1 inhibitors is accompanied by increased cell death and alterations in mitochondrial morphology and metabolic activity." (PMID 38980505, 2024). "PROTAC PU7-1, targeting FOXM1 through the involvement of USP7 (Ubiquitin Specific Peptidase 7), significantly reduces FOXM1 protein levels in breast cancer cells and inhibits cell proliferation in MDA-MB-468 (IC50 1.8 μM) and BT549 (IC50 2.8 μM) TNBC cells." (PMID 39594778, 2024). "Researches have showed that FOXM1 takes part in the progression in different tumors, such as liver cancer, ovarian carcinoma, breast cancer and colon cancer." (PMID 38967523, 2024). "FOXM1 is an oncogenic transcription factor that is greatly upregulated in breast cancer and many other cancers where it promotes tumorigenesis, cancer growth and progression." (PMID 39040191, 2024). "FOXM1, a proto-oncogenic transcription factor, plays a critical role in cancer development and treatment resistance in cancers, particularly in breast cancer." (PMID 38918225, 2024). "To further determine the critical roles of the USP22-FoxM1-integrin b1 in breast cancer pathogenesis, we utilize the immunohistochemistry staining determined the expression of USP22, FoxM1, and integrin b1 protein in human breast cancer tissue microarray." (PMID 37398311, 2023). "Expression analysis of FOXM1 by qRT-PCR in breast cancer cell lines confirmed FOXM1 upregulation in MCF-7 and MDA-MB-468 cells." (PMID 37025658, 2023). "FOXM1 (Forkhead box M1) is an oncogenic transcription factor that is greatly upregulated in breast cancer and many other cancers where it promotes tumorigenesis, and cancer growth and progression." (PMID 37370117, 2023). "Our data confirms that miR-4521 overexpression facilitates ROS induced DNA damage with reduced DNA repair capacity by FOXM1 downregulation in breast cancer." (PMID 37025658, 2023). "Recent studies in mouse breast cancer models showed that FoxM1 binds directly to the RB1 protein and forms repressive transcriptional complexes, which suppress the Pten tumor suppressor gene and are essential for tumor cell plasticity and metastasis." (PMID 37686402, 2023). "When analyzed against customary breast tissue, the FOXM1 transcript is more abundant in breast cancers." (PMID 37626655, 2023). "Analysis of tumors from HER2+ patients also showed that FOXM1 expression correlated with poor prognosis in this subtype of breast cancer." (PMID 37370117, 2023). "Conversely, data support a role for FOXM1 in mediating ACSL4-induced radioresistance in breast cancer cells." (PMID 37306503, 2023). "Conversely, loss of USP22 expression resulted in a significant increase in FoxM1 ubiquitination in both mouse 4T1 and patient-derived breast cancer cells." (PMID 37398311, 2023). "The c-Src/FOXM1 axis is a therapeutic target that correlates with poor outcomes for patients with luminal B breast cancer." (PMID 36795481, 2023). "For example, expression of HMGA1, which is known to promote breast cancer angiogenesis through the transcriptional activity of FOXM1, increased in a time-dependent manner." (PMID 36661191, 2023). "We also retrieved a study that, at first glance, did not contain an obvious connection to proinflammatory gene responses but rather investigated differences in gene expression after FOXM1 inhibition in MCF7 breast cancer cells for 0 (naive) versus 6 h." (PMID 36694664, 2023). "Further, we validated miR-4521 and FOXM1 interaction in breast cancer cell line MCF-7 using luciferase reporter assay." (PMID 37025658, 2023). "Collectively, these results indicate that USP22 promotes breast cancer metastasis at least partially, through promoting FoxM1-mediated integrin b1 expression." (PMID 37398311, 2023).
breast cancer (continued). "Upon DOX treatment for 2 h, breast cancer cells showed increase in the damage by γH2AX foci formation in miR-4521 expressed and FOXM1 inhibitor thiostrepton treated cells with delayed recovery rate even after 12 h when compared to control cells." (PMID 37025658, 2023). "In breast cancer models, FOXM1 blocked the phosphorylation of YAP at S127, thereby enhancing YAP’s nuclear localization and ability to promote the transcription of proliferation, migration, and cell stemness genes." (PMID 37686402, 2023). "The data presented here argue that coordinated activation of c-Src and FOXM1 is a targetable vulnerability in luminal B–like breast cancer." (PMID 36795481, 2023). "Consistent with this, silencing of FOXM1 by siRNA or treatment with FOXM1 small molecule inhibitors abolished estrogen-induced breast cancer cell proliferation." (PMID 37370117, 2023). "YTHDF1 promoted breast cancer metastasis by accelerating the translation of forkhead box M1 (FOXM1)." (PMID 36835633, 2023). "In conclusion, FOXM1 enhanced the advancement of mammary tumors through the Hippo pathway and can be utilized as a novel approach to treating breast cancer." (PMID 37626655, 2023). "FOXM1 plays a critical role in ROS scavenging and promotes stemness which contributes to drug resistance in breast cancer." (PMID 37025658, 2023). "Although M1-20 has been primarily studied for its anti-tumor effects in breast cancer models, it has the potential to inhibit various types of cancer by targeting the FOXM1 protein." (PMID 37598210, 2023). "These compounds also revealed that the coordinated activation of the tyrosine kinase c-Src and FOXM1 drives tumor cell proliferation and breast cancer progression." (PMID 37370117, 2023). "FOXM1 promotes EMT in breast cancer by activating the SLUG gene, and metastases through interaction with SMAD3 to activate the TGF-β pathway." (PMID 37025658, 2023). "FoxM1 has been identified as an integrin β1 transcription factor thereby promoting breast cancer progression 27, implying a possibility that USP22 controls breast cancer cell ITGB1 expression through FoxMl stabilization." (PMID 37398311, 2023). "Accordingly, analysis of The Cancer Genome Atlas (TCGA) breast cancer data revealed that expression of FOXM1 and SRC mRNAs correlated positively in patients’ tumor samples, particularly in luminal subtypes." (PMID 36795481, 2023). "Breast cancer cells tend to proliferate when ß‐actin, FOXM1, FBXW7, Fascin, eNOS, MMP‐2 and HER2‐receptor are expressed or stimulated." (PMID 37697969, 2023). "For example, as a result of gene amplification, FOXM1 is abnormally high expressed in basal-type breast cancer and diffuse large B-cell lymphoma." (PMID 36622275, 2023). "In the present study, a targeted treatment platform containing AuNPs as a carrier, FOXM1 Apt, AS1411, and ATP Apt was developed to treat breast cancer by co-delivery of Dox as a chemotherapy drug and FOXM1 Apt as a therapeutic aptamer to cancerous cells." (PMID 37736517, 2023). "ROC curve analysis of FOXM1 in TCGA-BRCA datasets showed its diagnostic potential to differentiate between normal and various subtypes of breast cancer samples." (PMID 37025658, 2023). "In order to liaise mitotic cataclysm and senescence in breast cancer cells, paclitaxel can also downregulate FOXM1." (PMID 37626655, 2023). "To further verify if FOXM1 is essential for aneuploid cells, we attempted to generate aneuploid cells by treating breast cancer cells with dihydrocytochalasin B (DCB), to block cytokinesis and induce tetraploidy." (PMID 37452072, 2023). "FOXM1 interacts directly with many of the major players and pathways that promote breast cancer growth and progression." (PMID 37370117, 2023). "During breast cancer progression, miR-671-5p, a tumor suppressor miRNA, targets FOXM1 expression and function in breast cancer cells." (PMID 37025658, 2023).
breast cancer (continued). "Our studies have also demonstrated that adenovirus-mediated interference with FOXM1 expression impedes the progression of liver cancer, breast cancer, and nasopharyngeal carcinoma." (PMID 37598210, 2023). "Our study has identified that miR-4521 overexpression perturbs FOXM1 mediated transcription regulation of cell cycle progression contributing to G1 arrest and ROS mediated DNA damage in breast cancer cells." (PMID 37025658, 2023). "FOXM1 is so ubiquitous in breast cancer that all subtypes produce the FOXM1 gene transcript that also happens to be indispensable for treatment resistance, the transition of epithelial cells to mesenchymal cells (EMT), annexation, and metastasis." (PMID 37626655, 2023). "Inhibition of FOXM1 function by miR-4521 contribute to impaired DNA repair in breast cancer cells leading to increased cell death." (PMID 37025658, 2023). "Among breast cancer subtypes, a consistent overexpression of FOXM1 is seen in triple-negative breast cancer (TNBC)." (PMID 37025658, 2023). "FOXM1 overexpression has been linked to doxorubicin resistance through the regulation of XIAP and Survivin in breast cancer cells." (PMID 37025658, 2023). "We observed that breast cancer cells stably expressing miR-4521 lead to cell cycle arrest, impaired FOXM1 mediated DNA damage response leading to increased cell death in breast cancer cells." (PMID 37025658, 2023). "A targeted delivery platform was prepared to co-deliver both doxorubicin (Dox) as an anticancer drug and FOXM1 aptamer as a therapeutic substance to breast cancer cells (4T1 and MCF-7) to reduce Dox side effects and increase its therapeutic efficacy." (PMID 37736517, 2023). "Using TCGA breast cancer data, we demonstrated that a FOXM1 target gene signature (including FOXM1) was enriched in poor-outcome luminal B, HER2+, and triple-negative breast cancer (TNBC) subtypes, but not in luminal A or normal-like subtypes." (PMID 36795481, 2023). "FOXM1 expression in breast cancer is a critical regulator of MELK, an oncogenic kinase, involved in cancer cell proliferation." (PMID 37025658, 2023). "Consistent with this, we observed that ectopic expression of FoxM1 largely restored the tumor sphere formation ability of USP22-deficent breast cancer cells." (PMID 37398311, 2023). "In breast cancer patients, Nijmegen breakage syndrome gene-targeting by FOXM1 can regulate senescence induced by DNA damage and epirubicin resistance." (PMID 37626655, 2023). "As an example, our results showed enrichment of RUNX1, ESR1, FOXA1, and FOXM1 target genes in breast cancer type-specific GRNs." (PMID 37627195, 2023). "Further investigation showed that only P5 (the sequence 709-728aa of FOXM1) significantly inhibited MDA-MB-231 breast cancer cells in a dose-dependent manner, providing a reason to focus on this peptide for further studies." (PMID 37598210, 2023). "The production of FOXM1 is upraised in breast cancer cells, and patients with breast cancer have a substandard prognosis and transient overall endurance as a result." (PMID 37626655, 2023). "High FOXM1 expression is correlated with chemoresistance in patients treated with doxorubicin and Epirubicin by enhancing the DNA repair in breast cancer cells." (PMID 37025658, 2023). "In silico analysis and functional assay confirmed FOXM1 as one of the targets of miR-4521 in breast cancer cells." (PMID 37025658, 2023). "Further, miR-4521 mediated FOXM1 downregulation impairs DNA damage response in breast cancer cells leading to increased cell death in breast cancer." (PMID 37025658, 2023). "The endogenous interaction between USP22 and FoxM1 in patient-derived breast cancer L2G+ TN1 cells was further validated." (PMID 37398311, 2023). "Here, we have shown that deletion of c-Src in a genetically engineered model mimicking the luminal B molecular subtype of breast cancer abrogated the activity of forkhead box M1 (FOXM1), a master transcriptional regulator of the cell cycle." (PMID 36795481, 2023).
breast cancer (continued). "Taken together, these findings support the efficacy of targeting FOXM1 in luminal B–like breast cancer." (PMID 36795481, 2023). "FOXM1 promotes EMT in breast cancer through direct binding and activation of the SLUG promoter, and it interacts with SMAD3 to sustain TGF-β-induced breast cancer metastasis." (PMID 37370117, 2023). "FOXM1 was previously reported to be involved in the DNA repair pathway in breast cancer cells, pancreatic cancer cells, and glioma cells." (PMID 37526082, 2023). "FOXM1 was also found to mediate breast cancer cell resistance to HER2-targeting agents, and inhibition of FOXM1 restored sensitization to trastuzumab." (PMID 37370117, 2023). "FOXM1 regulated KIF20A to modulate paclitaxel sensitivity in breast cancer, as well as in docetaxel resistance of prostate cancer." (PMID 36798768, 2023). "They contemplate that the FOXM1 (Forkhead Box 1), which is upregulated in breast cancer cells, exerts its oncogenic effects acting over the miRNA expression." (PMID 37925534, 2023). "Foci quantification per 100 nuclei per group provided the accurate DNA damage response measurement as the consequence of miR-4521 mediated inhibition of FOXM1 function in breast cancer cells." (PMID 37025658, 2023). "Another study identified that miR-802 directly target FOXM1 expression and function to inhibit the proliferation of breast cancer MCF-7 cells." (PMID 37025658, 2023). "Immunohistological staining of FOXM1 in tissue microarrays from breast cancer patients correlated with adverse clinicopathological features such as increased tumor size, lymph node metastasis, and higher tumor stage." (PMID 37370117, 2023). "FOXM1 overexpression indicates a poor prognosis in many cancers and promotes growth, invasion, metastasis, and resistance to endocrine therapy in breast cancer models." (PMID 36795481, 2023). "Targeting FOXM1 can thus be a promising therapeutic strategy to treat resistant, aggressive, metastatic breast cancers." (PMID 34981672, 2022). "High FOXM1 expression has been found in several types of cancer, including breast cancer, and the protein involves transcription activation and regulation of cell proliferation." (PMID 35681777, 2022). "NB73 is a small-drug FOXM1 inhibitor from the 1,1-diarylethylene class of compounds that effectively kills breast cancer cells containing high amounts of FOXM1." (PMID 35794249, 2022). "Recently, FOXM1 was also reported as an oncogene in a variety of cancers, including lung cancer, breast cancer, colorectal cancer, and HCC." (PMID 35887129, 2022). "FBXL19-AS1 as an oncogene can also develop breast cancer through other pathways since the upregulation of FBXL19-AS1 accelerates the expression of Forkhead box M1 (FOXM1) by sponging of miR-876-5p." (PMID 36649030, 2022). "NB73 is a 1,1-diarylethylene compound that binds FOXM1 and kills breast cancer cells that contain high amounts of the transcription factor." (PMID 35794249, 2022). "In breast cancer, FOXM1 was identified as a specific marker for TNBC and enhanced paclitaxel resistance in TNBC." (PMID 35524313, 2022). "In breast cancer cell lines, Survivin, as well as FOXM1 and XIAP have been shown to contribute to drug-resistance." (PMID 35331169, 2022). "FOXM1 recruits AURKA as a transcriptional factor that promotes breast cancer stem cell self-renewal and drug resistance." (PMID 35680842, 2022). "We found that a small compound called FDI-6 (forkhead domain inhibitor 6) is reported to inhibit the binding of FOXM1 to DNA in breast cancer cells." (PMID 36291764, 2022). "FOXM1 is highly expressed in several cancers, such as hepatocellular carcinomas, colon cancer, pancreatic cancer, gastric cancer, and breast cancer." (PMID 36101460, 2022).
breast cancer (continued). "The results confirmed that CDI alone was able to reduce the percentage of viable breast cancer cells by inhibiting FoxM1–DNA interaction." (PMID 35884976, 2022). "OTUB1 can also inhibit the ubiquitination of FOXM1, stabilize FOXM1 protein levels, downregulate FOXM1 protein levels in breast cancer, and increase the sensitivity of breast cancer cells to chemotherapeutic agents." (PMID 35494004, 2022). "In breast cancer, FOXM1 has a role in response to DNA damage, genotoxic drug resistance, and DNA damage-induced senescence." (PMID 36052073, 2022). "For instance, overexpression of miR-671-5p suppressed FOXM1 expression, thereby reducing breast cancer cells growth and invasion." (PMID 36200070, 2022). "The upregulation of miR-4731-5p suppressed the proliferation, migration, and invasion via targeting FOXM1 in breast cancer." (PMID 35342398, 2022). "Repression of Wnt3a/FOXM1/β-Catenin pathway is widely involved in the apoptotic impact of moracin D in breast cancer." (PMID 35799265, 2022). "Subsequently, FOXM1-WT and FOXM1-MUT plasmids were co-transfected into the breast cancer cells with Empty vector, YTHDF1-WT and YTHDF1-MUT plasmids, respectively." (PMID 35197112, 2022). "Clinical doses of ionizing radiation are known to stimulate the invasive properties of ErbB2-positive breast cancer cells and, moreover, radiation resulted in activation of ErbB2, which, through activation of FoxM1, promoted invasion of breast cancer cells." (PMID 35625825, 2022). "FOXM1 is a validated oncoprotein in solid and liquid cancers and governs, in part, the maintenance of cancer stem cell-like cells in breast cancer." (PMID 35794249, 2022). "This is consistent with the observation that elevated expression of FOXM1 in breast cancer strongly correlates with ERα expression." (PMID 34831091, 2021). "They inhibited the proliferation of a variety of breast cancer cells expressing FOXM1 and increased apoptosis." (PMID 34944900, 2021). "We therefore propose that SHR6390 combined with pyrotinib inhibits the proliferation of HER2+/HR+ breast cancer through regulation of the FOXM1." (PMID 34977029, 2021). "Both FOXA1 and FOXM1 showed a significant upregulation in luminal A breast cancer subtype compared with normal breast tissues." (PMID 34425866, 2021). "Conversely, depletion of FOXM1 and NBS1 through an si-RNA approach led to the loss of HR repair ability in breast cancer cells, resulting in accumulation of γH2AX foci and induction of cellular senescence." (PMID 34680943, 2021). "In another case study of breast cancer, FOXM1, a drugable target, was identified as a key regulator underlying breast cancer progression and, importantly, the predicted FOXM1-target regulations were validated." (PMID 33667222, 2021). "Previously, several researches have shown that FOXM1 is overexpressed in multiple cancers, such as breast cancer, ovarian cancer, colon cancer, liver cancer, pancreatic cancer, ovarian cancer and gastric cancer." (PMID 33391456, 2021). "FoxM1 is aberrantly high-expressed in almost all solid cancers in our data analysis, like bladder cancer, breast cancer, sarcoma, colorectal cancer and lung cancer." (PMID 33526768, 2021). "Here, we show that RASSF1A decreases the levels of YAP1, and as a consequence, the suppression of FOXM1 and ERα expression and senescence in ERα-driven breast cancer cells." (PMID 34831091, 2021). "Treatment of HER2-positive breast cancer with the HER2/EGFR inhibitor lapatinib leads to decreased FOXM1 expression, suggesting that HER2 positively regulates FOXM1." (PMID 33920089, 2021). "Accumulating studies have reported the involvement of FOXM1 in the progression of tumors including lung cancer, gastric cancer, breast cancer, and epithelial ovarian cancer." (PMID 35036134, 2021). "Regarding TNBC, the FOXM1 expression was discovered to be higher when compared with other breast cancer types." (PMID 34206484, 2021).